FNIP2 (folliculin interacting protein 2)
Description:
Binding partner of the GTPase-activating protein FLCN: involved in the cellular response to amino acid availability by regulating the non-canonical mTORC1 signaling cascade controlling the MiT/TFE factors TFEB and TFE3. Required to promote FLCN recruitment to lysosomes and interaction with Rag GTPases, leading to activation of the non-canonical mTORC1 signaling (By similarity). In low-amino acid conditions, component of the lysosomal folliculin complex (LFC) on the membrane of lysosomes, which inhibits the GTPase-activating activity of FLCN, thereby inactivating mTORC1 and promoting nuclear translocation of TFEB and TFE3. Upon amino acid restimulation, disassembly of the LFC complex liberates the GTPase-activating activity of FLCN, leading to activation of mTORC1 and subsequent inactivation of TFEB and TFE3. Together with FLCN, regulates autophagy: following phosphorylation by ULK1, interacts with GABARAP and promotes autophagy. In addition to its role in mTORC1 signaling, also acts as a co-chaperone of HSP90AA1/Hsp90: inhibits the ATPase activity of HSP90AA1/Hsp90, leading to activate both kinase and non-kinase client proteins of HSP90AA1/Hsp90. Acts as a scaffold to load client protein FLCN onto HSP90AA1/Hsp90. Competes with the activating co-chaperone AHSA1 for binding to HSP90AA1, thereby providing a reciprocal regulatory mechanism for chaperoning of client proteins. May play a role in the signal transduction pathway of apoptosis induced by O6-methylguanine-mispaired lesions (By similarity).
Synonyms: FNIPL; KIAA1450; MAPO1
Tractability: Small molecule: a structure with a bound ligand is known. PROTAC: ubiquitination databases record sites on it.
Gene: Protein-coding gene on chromosome 4 (158,769,026 to 158,908,050, forward strand). Ensembl gene ENSG00000052795.
Subcellular location: Lysosome membrane; Cytoplasm
Subcellular location (Human Protein Atlas): Cytosol; Centriolar satellite
Pathways (Reactome):
Cellular responses to stimuli: Amino acids regulate mTORC1
Gene Ontology:
Molecular function: ATPase inhibitor activity; protein binding; protein-folding chaperone binding
Biological process: negative regulation of transcription by RNA polymerase II; positive regulation of protein-containing complex assembly; positive regulation of TORC1 signaling; intrinsic apoptotic signaling pathway in response to DNA damage; negative regulation of TOR signaling
Cellular component: centriolar satellite; cytoplasm; cytosol; FNIP-folliculin RagC/D GAP; lysosomal membrane
Genetic constraint (gnomAD): Loss-of-function variants: 30 observed, 96.96 expected, observed/expected ratio (o/e) 0.31, 90% interval 0.23 to 0.42. The upper end of that interval is the gene's LOEUF score, 0.42, which puts it in group 1 of 6, group 1 being the genes least tolerant of losing a copy. Missense variants: 1,174 observed, 1,379.7 expected, observed/expected ratio (o/e) 0.85, 90% interval 0.81 to 0.89. Synonymous variants: 467 observed, 499.73 expected, observed/expected ratio (o/e) 0.93, 90% interval 0.87 to 1.01.
Homologues: Orthologues: chimpanzee FNIP2 (96% identical), macaque FNIP2 (96% identical), dog FNIP2 (82% identical), mouse Fnip2 (78% identical), rat Fnip2 (77% identical), rabbit FNIP2 (76% identical), pig FNIP2 (76% identical), guinea pig FNIP2 (72% identical), tropical clawed frog fnip2 (56% identical), zebrafish fnip2 (45% identical), Drosophila melanogaster CG3764 (25% identical), Caenorhabditis elegans fnip-2 (17% identical). Paralogues in human: FNIP1 (51% identical).
Diseases named in the same sentence as FNIP2 in open-access papers:
FNIP2 is named in the same sentence as 14 diseases in open-access papers, as found by Europe PMC text mining. Sharing a sentence is not in itself a finding about the gene and the disease. The quoted sentences say what the papers report.
Obesity (3 papers, 2021 to 2024). Accumulation of substantial excess body fat. "Consistently, T carriers of rs2291007 showed diminished FNIP2 expression in peripheral blood, and importantly, its expression strongly associates with decreased obesity-related metabolic parameters." (PMID 36316722, 2022). "For first time, this study describes that the minor allele T of rs2291007 in the FNIP2 gene is associated with metabolic and obesity-related phenotypes (elevated fat mass, visceral fatness, weight, BMI, and waist and hip circumferences) and with decreased muscle mass in healthy European individuals." (PMID 36316722, 2022). "Moreover, in addition to the genetic association, the levels of FNIP2 mRNA inversely correlate with anthropometric and clinical features of obesity." (PMID 36316722, 2022). "Thus, we propose that both rs2291007 and FNIP2 blood mRNA levels are linked to obesity." (PMID 36316722, 2022). "CR increased transcripts of both TFE3 and FNIP2 in Control females only, while Obesity prevented the CR-induced increases." (PMID 38166559, 2024). "RILP and FNIP2 were associated to a SI score > 20 and PLIN2 was associated with obesity in the two families." (PMID 33807278, 2021). "The polymorphism rs2291007 is located in the 3′UTR of the FNIP2 locus, and it has not been previously associated in the literature with overweight or obesity." (PMID 36316722, 2022). "We found an association between multiple metabolic parameters related to obesity and a human-specific SNP within an evolutionarily conserved region of the 3′UTR of the folliculin-interacting protein 2 (FNIP2) that affects mRNA stability." (PMID 36316722, 2022). "Lysosomal changes in males were surprisingly absent, with the exception of a trending decrease in FNIP2 mRNA in Obese males with CR, further highlighting the discrepancies between female and male responses to obesity and CR." (PMID 38166559, 2024).
renal tumor (3 papers, 2010 to 2021). "FNIP2, as the highest combined score node in ceRNA, was identified to play an important role in kidney tumor suppression, whereas its function in LUAD remains unclear." (PMID 34617407, 2021). "This study will shed light on the understanding of FLCN/FNIP1/FNIP2/AMPK function and the downstream target genes and signaling pathways that are important in tumorigenesis, providing insight into therapeutic targets for treatment of renal tumors that develop in BHD syndrome and translocation RCC." (PMID 21209915, 2010).
polycystic kidneys (2 papers, 2017 to 2023). "Recent studies indicated that FNIP1/FNIP2 double knockout mice display enlarged polycystic kidneys and renal carcinoma, which phenocopies FLCN knockout mice, suggesting that these two proteins function together to suppress renal cancer." (PMID 28039480, 2017).
renal carcinoma (2 papers, 2017 to 2025). A carcinoma arising from the epithelium of the renal parenchyma or the renal pelvis. "Degradation of FNIP2 leads to lysosomal dissociation of FLCN and subsequent lysosomal association of mTOR, which in turn promotes the proliferation of renal cancer cells." (PMID 28039480, 2017). "Heterozygous FNIP1/homozygous FNIP2 double knockout mice developed renal cancer at 24 months, akin to heterozygous FLCN knockout mouse models, thereby reinforcing the significance of FNIP1 and Fnip2 in tumor suppression and suggesting potential molecular targets for novel renal cancer therapies." (PMID 40143966, 2025). "Reintroducing FNIP2-WT conversely blocked colony formation of the FNIP-depleted UOK-257-2 cells whereas reintroducing the FNIP2-3A mutant further suppressed cell growth, suggesting a tumor suppressive role of FNIP2 and a contribution of β-TRCP in promoting renal cancer cell proliferation." (PMID 28039480, 2017). "To investigate the role of β-TRCP-mediated FNIP degradation in renal cancer cell growth, we manipulated UOK-257-2 cells by depleting FNIP1/FNIP2 and reintroducing FNIP2-WT or non-degradable FNIP2-3A." (PMID 28039480, 2017).
kidney cancer (1 paper, 2021). Primary or metastatic malignant neoplasm involving the kidney. "When FNIP1 and FNIP2 are inactivated simultaneously, mice develop kidney cancer." (PMID 33459596, 2021).
melanoma (1 paper, 2025). A malignant, usually aggressive tumor composed of atypical, neoplastic melanocytes. "The correlation between MITF and RRAGD and FNIP2 mRNA expression was reproduced using The Cancer Genome Atlas (TCGA) melanoma cohort." (PMID 41275493, 2025).
morbid obesity (1 paper, 2024). An excess of body weight, normally defined as an individual with a body mass index greater than 35 or a body weight greater than one hundred percent of ideal body weight. "Most of these genes, such as transcription factor family genes Mybl1 and Fnip2, are related to the occurrence and development of T2DM and morbid obesity." (PMID 38396669, 2024).
tumor (12 papers, 2016 to 2025). "Notably, our upregulated genes also included FNIP1 and FNIP2, encoding folliculin-interacting proteins 1 and 2, emphasizing the potential importance of this pathway in NB tumor suppression." (PMID 32537432, 2020). "The dual inactivation of FNIP1/2 in mouse kidneys leads to polycystic kidney enlargement akin to FLCN deficiency, highlighting their roles as tumor suppressors, as mice with FNIP1 and/or FNIP2 knockouts exhibit tumors in multiple organs." (PMID 40143966, 2025). "FNIP2 is a tumor suppressor gene that has been shown to be involved in regulating the apoptosis signaling pathway in tumors and is responsible for cellular metabolism and nutrient sensing." (PMID 29618726, 2018). "Reintroducing FNIP2-WT in FNIP1/FNIP2 depleted cells resulted in decreased tumor size and FNIP2-3A mutant presented further suppressive effects." (PMID 28039480, 2017). "FNIP1 and FNIP2 were also found to be critical for the tumor-suppressive function of FLCN in kidney tissue, suggesting that the appearance of tumors in BHD patients may be caused by the loss of essential FLCN-FNIP interactions." (PMID 32195250, 2020). "Thus, functional studies have shown that FNIP1 and FNIP2 act as tumor suppressors since mice deficient in FNIP1 and FNIP2 tumors display tumors developing at the level of several organs." (PMID 32751108, 2020). "The tumor suppressor FLCN and its binding partner FNIP2 comprise the primary GAP complex activating RagC/D and are accordingly crucial for the phosphorylation of TFEB/TFE3 by mTORC146,50." (PMID 36357396, 2022). "We also examined tumor xenograft growth in FLCN-depleted, TSC2 KO cells stably expressing FLCNF118D or a combination of FLCNF118D/ FNIP2." (PMID 36357396, 2022). "Importantly, FNIP1 and FNIP2 were essential also for the tumor suppressive function of FLCN at the level of kidney tissue, thus supporting the view that the development of kidney tumors in BHD patients may be due to the loss of essential FLCN-FNIP interactions." (PMID 32751108, 2020). "Several genes splicing events, including KIAA1715/56096/AP, ZNF567/49415/AP, NTMT1/87861/AP, ANAPC15/17570/AD, SRPK2/81284/ES, MTMR11/7413/AP, FNIP2/70999/AP, and TNC/87336/ES, differed significantly between tumor and normal samples." (PMID 31552163, 2019). "Here we show that the tumour suppressor FLCN is an Hsp90 client protein and its binding partners FNIP1/FNIP2 function as co-chaperones." (PMID 27353360, 2016). "Previous work has shown that FNIP1 and FNIP2 are critical components of the FLCN complex and are essential for its tumour suppressive function." (PMID 27353360, 2016). "In renal tumors, loss of FLCN-FNIP1/2 induces a non-classical interferon response, and FNIP1 and FNIP2 are crucial for FLCN’s tumor suppressor function." (PMID 37341987, 2023). "Considering the close relationship between the FNIPs and FLCN it is not surprising that they have also been suggested to act as tumor suppressors, as mice deficient in FNIP1 and/or FNIP2 exhibit tumors in several different organs." (PMID 32195250, 2020). "Our data showed that both FNIP1 and FNIP2 were overexpressed in RCC tumours compared with adjacent normal tissues." (PMID 27353360, 2016). "FLCN has been shown to bind FNIP1, FNIP2, the Rag GTPases A and C/D, GABARAP and plakophilin-4 (refs 11, 12, 13, 14, 15, 16, 17, 18), but the biological significance of each of these interactions with regards to the tumour suppressor function of FLCN is under investigation." (PMID 28656962, 2017). "Notably, FNIP1/FNIP2 double knockdown promoted cell proliferation and migration, which were suppressed by reintroducing the non-degradable FNIP2 mutant, validating the critical tumor suppressor role of FNIP proteins." (PMID 28039480, 2017).
tumor (continued). "Our data indicate that a negative feedback loop constrains amino acid-induced, FLCN:FNIP2-mediated RagC activity in renal cells with constitutive mTORC1 signaling, and the resulting MiT/TFE hyperactivation may drive oncogenesis with loss of the TSC2 tumor suppressor." (PMID 36357396, 2022). "Tumor growth was modestly, although non-significantly, suppressed in cells stably expressing FLCNF118D/ FNIP2 consistent with the more attenuated rescue of TFEB phosphorylation in vivo compared to what was observed in vitro, potentially due to issues with long-term expression of these constructs." (PMID 36357396, 2022).
cancer (5 papers, 2016 to 2025). A tumor composed of atypical neoplastic, often pleomorphic cells that invade other tissues. "The T-to-C variant represents the major allele in Europeans and disrupts an ancestral target sequence of the miRNA miR-181b-5p, thus resulting in increased FNIP2 mRNA levels in cancer cell lines and in peripheral blood from carriers of the C allele." (PMID 36316722, 2022). "To link the high levels of FNIPs with sensitivity of cancer cells to Hsp90 inhibitors, we used siRNA to knock down FNIP1 and FNIP2 in LNCaP, T24, MCF7, H1299 and HT29 cells." (PMID 27353360, 2016). "In the Cancer Cell Line Encyclopedia (CCLE), expression of FNIP2 and RRAGD, and to some extent RRAGC, but not RRAGA or RRAGB, correlates with MITF expression." (PMID 41275493, 2025). "Interestingly, although the targeted deletion of Fnip2 in mice does not result in observable phenotypes, kidney-specific disruption of both Fnip1 and Fnip2 leads to severe PKD, which eventually progresses to cancer." (PMID 40699689, 2025).
FNIP2 also shares sentences with these, for which no sentence is quoted: Renal cyst (2 papers); ataxia telangiectasia (1); depression (1); prostate carcinoma (1); schizophrenia (1).